JPH4 (junctophilin 4)
Description:
Junctophilins contribute to the formation of junctional membrane complexes (JMCs) which link the plasma membrane with the endoplasmic or sarcoplasmic reticulum in excitable cells. Provides a structural foundation for functional cross-talk between the cell surface and intracellular calcium release channels. JPH4 is brain-specific and appears to have an active role in certain neurons involved in motor coordination and memory (By similarity).
Synonyms: JPHL1; KIAA1831; JP4
Tractability: Antibody: UniProt places it where antibodies can reach, with medium confidence; UniProt predicts a signal peptide or a membrane-spanning region; its Gene Ontology location is reachable by antibodies, with medium confidence. PROTAC: its protein half-life has been measured.
Gene: Protein-coding gene on chromosome 14 (23,568,038 to 23,578,790, reverse strand). Ensembl gene ENSG00000092051.
Subcellular location: Cell membrane; Endoplasmic reticulum membrane
Subcellular location (Human Protein Atlas): Cytosol
Gene Ontology:
Molecular function: protein binding
Biological process: calcium ion transport into cytosol; regulation of cardiac muscle contraction by calcium ion signaling; regulation of release of sequestered calcium ion into cytosol by sarcoplasmic reticulum; regulation of synaptic plasticity
Cellular component: endoplasmic reticulum membrane; junctional membrane complex; junctional sarcoplasmic reticulum membrane; plasma membrane; dendritic shaft; smooth endoplasmic reticulum
Genetic constraint (gnomAD): Loss-of-function variants: 18 observed, 31 expected, observed/expected ratio (o/e) 0.58, 90% interval 0.4 to 0.86. The synonymous counts are far from expectation, so gnomAD's model fits this gene poorly and the ratio says little. Missense variants: 725 observed, 646.87 expected, observed/expected ratio (o/e) 1.12, 90% interval 1.05 to 1.19. Synonymous variants: 425 observed, 302.26 expected, observed/expected ratio (o/e) 1.41, 90% interval 1.3 to 1.52.
Homologues: Orthologues: chimpanzee JPH4 (100% identical), macaque JPH4 (99% identical), dog JPH4 (97% identical), rat Ap1g2 (96% identical), mouse Jph4 (96% identical), guinea pig JPH4 (96% identical), pig JPH4 (96% identical), Caenorhabditis elegans jph-1 (37% identical), Drosophila melanogaster jp (32% identical). Paralogues in human: JPH3 (44% identical), JPH2 (42% identical), JPH1 (41% identical).
Diseases named in the same sentence as JPH4 in open-access papers:
JPH4 is named in the same sentence as 5 diseases in open-access papers, as found by Europe PMC text mining. Sharing a sentence is not in itself a finding about the gene and the disease. The quoted sentences say what the papers report.
Cirrhosis (1 paper, 2022). A chronic disorder of the liver in which liver tissue becomes scarred and is partially replaced by regenerative nodules and fibrotic tissue resulting in loss of liver function. "Another cirrhosis-related gene, JPH4, found in liver tissue, is located at 14q11.2." (PMID 35646080, 2022).
infection (1 paper, 2025). The state of being infected such as from the introduction of a foreign agent such as serum, vaccine, antigenic substance or organism. "We also analyzed the differential expression of JPH4 and CYP1A1 during the early stages of infection in iPMAs and PAMs." (PMID 41425566, 2025).
tumour (1 paper, 2020). "Furthermore, miR-205 represses the tumour suppressor gene JPH4, promoting tumorigenesis and tumour progression." (PMID 32523655, 2020).
JPH4 also shares sentences with these, for which no sentence is quoted: hyperlipidemia (1 paper); Obesity (1).